BTG2 (BTG anti-proliferation factor 2)
Diseases named in the same sentence as BTG2 in open-access papers (continued):
Sharing a sentence is not in itself a finding about the gene and the disease.
prostate carcinoma (continued). "Our previous in vitro study revealed that expression of BTG2 is related to neoplasia of human prostate carcinoma cells and forced-overexpression of BTG2 in prostate carcinoma PC-3 cells attenuated cell proliferation." (PMID 24586533, 2014). "Previous studies have shown that BTG2 did play an important role to repress cell growth in gastric, breast, bladder, and prostate carcinoma cells." (PMID 24586533, 2014). "In breast and prostate carcinomas, where BTG2 expression was found to be reduced, therapies restoring BTG2 expression may contribute to the inhibition of cancer cell proliferation." (PMID 30350856, 2019). "Moreover, BTG2 is also among a set of genes whose expression pattern can be used as a biomarker to predict the recurrence of prostate cancer." (PMID 30350856, 2019). "BTG2 has been related to pancreatic cancer, and the relation between miR-21 and BTG2 interaction has been observed in other cancers (multiple myeloma, liver cancer, prostate cancer), but they still have not been directly linked in pancreatic cancer." (PMID 29464088, 2018). "Cisplatin up-regulated BTG2-attenuated prostate cancer cell proliferation." (PMID 30115961, 2018). "For example, in prostate cancer it was shown that the induction of cells by T3 can increase the proliferation of tumor cells by reducing the B-cell translocation gene 2 (BTG2) gene expression which is responsible for the regulation of the G1/S transition in the cell cycle." (PMID 27034829, 2016). "Hypomethylation of tumor suppressor genes, such as BTG2 and DKK3, in the tumor group results in decreased gene expression, contributing to prostate cancer proliferation." (PMID 40265030, 2025). "Our results showed that the expression levels of SEMA3B and BTG2 in the TSPX-high prostate cancer samples were similar with those in the non-tumor prostate samples (P-value > 0.05), while those in TSPX-low prostate cancer samples were significantly low." (PMID 30863497, 2019). "Our objectives for this study were to determine the effects and regulatory mechanisms of CPT and DOX on the gene expression of BTG2 and PSA in prostate cancer cells." (PMID 24586533, 2014). "We evaluated the molecular mechanisms of CPT and DOX on cell proliferation and the expressions of BTG2 and prostate specific antigen (PSA) in prostate carcinoma cells." (PMID 24586533, 2014). "In castration-resistant prostate cancer, for example, miR-32 is up-regulated by androgen, targets PI3K inhibitor PIK3IP1, and tumor suppressor BTG2." (PMID 24029073, 2013).
gastric cancer (21 papers, 2016 to 2025). A primary or metastatic malignant neoplasm involving the stomach. "MiR-21 and its targets FASLG and B-cell translocation gene 2 (BTG2) are implicated in the malignant progression of MNNG-induced gastric cancer." (PMID 38460046, 2024). "The researchers found that BTG2 is closely associated with the metastasis and progression of non-small cell lung cancer and gastric cancer." (PMID 34545330, 2021). "High expression levels of BTG2 and decreased nucleolin expression are associated with better overall survival in patients with poorly differentiated gastric cancer." (PMID 33804551, 2021). "The miR-27a-3p/BTG2 axis is believed to be promising as not only a diagnostic biomarker for patients with gastric cancer but also a potential therapeutic target for gastric cancer." (PMID 31956102, 2020). "Overall, these results suggested that the miR-27a-3p/BTG2 axis might represent a promising diagnostic biomarker for gastric cancer patients and could be a potential therapeutic target in the management of gastric cancer." (PMID 27409164, 2016). "Recent studies have demonstrated that BTG2 can be regulated by non-coding RNAs, including miRNAs, however its association with mature miR-27a in gastric cancer remains unknown." (PMID 27409164, 2016). "Notably, BTG2 has been implicated in cell proliferation, apoptosis, and invasion of gastric cancer." (PMID 27409164, 2016). "For instance, TEAD4-activated MNX1-AS1 has been shown to facilitate gastric cancer progression through the EZH2/BTG2 and miR-6785-5p/BCL2 axes." (PMID 39735666, 2025). "qRT-PCR results showed that as compared to GES-1, BTG2 expression was significantly lower in six gastric cancer cell lines." (PMID 36841760, 2023). "miR-27a-3p also exerts carcinogenic effects in gastric cancer and can affect the cycle and apoptosis of gastric carcinoma cells via targeting B cell translocation gene 2 (BTG2)." (PMID 37958388, 2023). "Our study found that the expression of BTG2 was downregulated in gastric cancer tissues and cells, and that miR-15a-5p regulated its expression." (PMID 36841760, 2023). "Our study also included bioinformatics analyses which determined that the high expression of hsa_circ_0069382 regulated the BTG anti-proliferation factor 2 (BTG2)/ focal adhesion kinase (FAK) axis in gastric cancer lines by sponging for miR-15a-5p." (PMID 36841760, 2023). "This was consistent with BTG2 expression levels in paired and unpaired gastric cancer samples in TCGA." (PMID 36841760, 2023). "Our study confirmed that miR-15a-5p is highly expressed in gastric cancer tissues and cells, and promotes cancer by targeting the BTG2/FAK axis." (PMID 36841760, 2023). "Zhang et.al demonstrated that BTG2 is down-regulated in gastric cancer tissue, and overexpression of BTG2 suppresses the proliferation and migration of gastric cancer cells." (PMID 34861847, 2021). "Previous studies have reported that BTG2 is lowly expressed in many malignancies, e.g., lung cancer, hepatocellular carcinoma and gastric cancer, and functions as a possible target for malignancy prevention and treatment." (PMID 34082648, 2021). "For instance, MNX1-AS1 overexpression promotes gastric cancer progression via the EZH2/BTG2 and miR-6785-5p/BCL2 axis." (PMID 33882027, 2021). "It functions as an oncogene and promotes gastric cancer progression both in vitro and in vivo through downregulation of BTG2, demonstrating its ability to modulate malignant biological behavior." (PMID 31534967, 2019). "In turn, the biological effects of miR-27a-3p/BTG2 axis on gastric cancer cell proliferation and tumor growth resulted from G1/S cell cycle arrest, subsequent apoptosis, and C-myc activation following Ras/MEK/ERK signaling pathway." (PMID 27409164, 2016). "Further experiments revealed that BTG2 was a direct and functional target of miR-27a-3p in gastric cancer and miR-27a-3p inhibition obviously up-regulated the expression of BTG2." (PMID 27409164, 2016).
gastric cancer (continued). "It has been reported that BTG2 acts as a tumor suppressor in several human malignant tumors including gastric cancer." (PMID 27409164, 2016). "Based on a dual-luciferase reporter assay, we confirmed that miR-27a-3p directly target to the 3′-UTR region of BTG2 transcript in human gastric cancer." (PMID 27409164, 2016). "Western blot analysis confirmed low expression levels of BTG2 in gastric cancer cells." (PMID 36841760, 2023). "Additionally, BTG2 was identified as a direct target gene of miR-27a-3p in gastric cancer, and overexpression of BTG2 arrested the cell cycle of gastric cancer cells at the G1 phase and induced cell apoptosis." (PMID 33425718, 2020). "B-cell translocation gene 2 (BTG2) is a direct functional target of miR-27a-3p in gastric cancer." (PMID 31235820, 2019). "As the miR-27a-3p-induced cell growth we found in gastric cancer, we went on to investigate whether BTG2 functions downstream of miR-27a-3p in regulating the proliferation of GC cells." (PMID 27409164, 2016). "As a result, the expression of C-myc reversely correlated with BTG2 expression in gastric cancer tissues and cell lines, and similar to miR-27a-3p inhibition, overexpression of BTG2 decreased the expression of C-myc and Ras/MEK/ERK downstream proteins (Ras, p-MEK, and p-ERK)." (PMID 27409164, 2016). "The results from our in vitro experiments also suggested that the miR-27a-3p/BTG2 axis could affect C-myc activation following Ras/MEK/ERK signaling pathway in gastric cancer." (PMID 27409164, 2016). "Importantly, our further analysis in gastric cancer tissues also found that miR-27a-3p expression inversely correlated with BTG2 mRNA expression." (PMID 27409164, 2016). "Therefore, we hypothesized that miR-27a-3p/BTG2 axis could regulate C-myc expression via Ras/MEK/ERK signaling pathway in gastric cancer cells." (PMID 27409164, 2016). "Correlation analysis of miRNA and mRNA in TCGA database showed that miR-15a-5p negatively correlated with BTG2 expression, and miR-15a-5p positively correlated with FAK expression in gastric cancer." (PMID 36841760, 2023). "In conclusion, our study showed that hsa_circ_0069382 sponged miR-15a-5p to regulate the expression of BTG2/FAK, affecting the proliferation, invasion, and migration of gastric cancer." (PMID 36841760, 2023). "As shown in Graphical Abstracts, high hsa_circ_0069382 expression inhibited gastric cancer cell proliferation, invasion, and migration by downregulating miR-15a-5p and FAK, and upregulating BTG2." (PMID 36841760, 2023). "In this study, we established that hsa_circ_0069382 regulates the expression of BTG2/FAK by sponging miR-15a-5p, thus affecting the proliferation, invasion, and migration of gastric cancer." (PMID 36841760, 2023). "Despite having two mature isoforms, miR-27b-3p was found overexpressed in gastric cancer and noticeably promoted cell proliferation as well as tumour growth by targeting BTG Anti-proliferation factor 2 (BTG2)." (PMID 36768818, 2023). "MNX1-AS1 activated by TEAD4 can promote the GC process through EZH2/BTG2 and miR-6785-5p/BCL2 axes, suggesting that it was a novel and effective therapeutic target for gastric cancer." (PMID 34712264, 2021). "Notable targets up-regulated by PKNOX2 include BTG2, a tumor suppressor with anti-proliferative and anti-metastatic properties, and RPRM, which has been reported to suppress tumorigenesis in gastric cancer." (PMID 30745575, 2019). "qRT-PCR results of 68 pairs of gastric cancer and adjacent tissues showed that BTG2 expression was not significantly different between them, possibly because of the small number of tissue samples." (PMID 36841760, 2023). "As a tumor suppressor, BTG2 has been found to be down-regulated or absent in a variety of tumors, such as gastric cancer, breast cancer, and melanoma." (PMID 27409164, 2016).
gastric cancer (continued). "BTG2 attracted our attention because its 3′-UTR contains two putative target sequences for miR-27a-3p, and BTG2 is regarded as a tumor suppressor gene and closely involved in cell proliferation, apoptosis and invasion of several cancers cells, especially, of gastric cancer cells." (PMID 27409164, 2016). "However, till now, the link between miR-27a and BTG2 in gastric cancer has not been reported." (PMID 27409164, 2016).
lung cancer (21 papers, 2013 to 2025). A malignant neoplasm involving the lung. "Previous studies showed that BTG2 was significantly downregulated and linked with poor lung cancer patient prognosis." (PMID 36157236, 2022). "Wei found that overexpression of BTG2 can inhibit the proliferation and invasion of some tumors, including lung cancer cells." (PMID 37006240, 2023). "It has been shown that overexpression of BTG2 in lung cancer cells leads to an increase in the number of DDR-inducedγ-H2AX lesions." (PMID 37547297, 2023). "In the non-small-cell lung cancer models, overexpression of BTG2 prevented the lung cancer cell metastasis by inhibiting cell invasion." (PMID 37488455, 2023). "It is indicated that NUSAP1 knockdown inhibited cell growth and metastasis via regulating BTG2/PI3K/AKT signaling in nonsmall-cell lung cancer." (PMID 34782617, 2021). "For instance, BTG2 was highly expressed in lung cancer and promoted the proliferation and metastasis of tumor cells." (PMID 34580602, 2021). "For instance, the inflammation-related gene BTG2 was found to be lowly expressed in lung cancer and its overexpression suppressed the proliferation and metastasis of LUAD cells." (PMID 34580602, 2021). "First, over‐expression of BTG2 is known to inhibit proliferation of cells and invasion in some tumours, including lung cancer cells, and acts as an anti‐proliferation gene in cooperation with PRMT1." (PMID 29656435, 2018). "Further, we performed a meta‐analysis to examine the relationship between BTG2 expression and overall survival from the four consortium cohorts and 17 external public lung cancer cohorts." (PMID 29656435, 2018). "In this study, we investigated a potential role for BTG2 in early‐stage non‐small cell lung cancer (NSCLC) survival." (PMID 29656435, 2018). "In addition, the expression level of BTG2 is negatively correlated with activated mast cells in lung cancer had been identified." (PMID 40313959, 2025). "All these findings indicated that BTG2 is a potential lung cancer tumor suppressor." (PMID 36157236, 2022). "To understand the activity of BTG2 in lung cancer, we transfected BTG2 into A549 cells." (PMID 36157236, 2022). "BTG2 possesses anti-proliferation and anti-invasion functions in human lung cancer cells." (PMID 29416786, 2018). "However, the study of BTG2 in lung cancer has been limited to cell lines." (PMID 29656435, 2018). "Wei et.al demonstrated that overexpression of BTG2 inhibits the protein expression of cyclin D1, MMP-1, and MMP-2, and inhibit the growth, proliferation, and invasiveness of the A549 human lung cancer cell line." (PMID 34861847, 2021). "We analysed BTG2 methylation data from 1230 early‐stage NSCLC patients from five international cohorts, as well as gene expression data from 3038 lung cancer cases from multiple cohorts." (PMID 29656435, 2018). "In contrast, lung cancer samples express high levels of PRMT5, WDR77, ErbB2, ErbB3 and FGFR3 and decreased levels of GLIPR1, Leprel1 and BTG2." (PMID 27480244, 2016). "No studies have focused on the role of BTG2 in lung cancer prognosis, and no Lung Cancer cohort to date has validated its prognostic value." (PMID 29656435, 2018). "The overexpression of BTG2 may inhibit the growth and proliferation through inhibiting the protein expression of cyclin D1, and invasiveness through inhibiting the protein expression of MMP-1 (matrix metalloproteinase-1) and MMP-2 (matrix metalloproteinase-2) in the A549 human lung cancer cell line." (PMID 26132560, 2015).
pancreatic cancer (18 papers, 2018 to 2024). "Exosomal miRNA-27a derived from pancreatic cancer cells promotes the angiogenesis of human microvascular endothelial cells in pancreatic cancer via regulating BTG2." (PMID 38612727, 2024). "To further investigate the mechanism of the inhibition of progression of pancreatic cancer by miR-365/BTG2 mediated by BA, we first measured the expression of BA-mediated miR-365/BTG2 in two pancreatic cancer cell lines." (PMID 37415745, 2023). "Further, BTG2 expression and disease-free survival rate of pancreatic cancer is positively correlated." (PMID 36765032, 2023). "To sum up, we discover that BA inhibits the expression of IL-6 and phosphorylation of AKT/STAT3 by mediating changes in miR-365/BTG2, thereby inhibiting the progression of pancreatic cancer." (PMID 37415745, 2023). "On this basis, we evaluated the changes in the level of BTG2 mRNA in the BA-mediated pancreatic cancer animal model." (PMID 37415745, 2023). "In transcriptomic analysis of mouse pancreatic tumor tissue, we identified BTG2 as a tumor suppressor gene whose expression was significantly induced by treatment with both T1-44 and Vactosertib in a mouse pancreatic tumor model." (PMID 36765032, 2023). "Among these genes,BTG2 is underexpressed in pancreatic cancer, while its overexpression suppresses pancreatic cancer cell growth and enhances cancer cell apoptosis." (PMID 36789695, 2022). "In conclusion, the DSCR9/miR-21-5p/BTG2 axis modulates pancreatic cancer proliferation, invasion, and gemcitabine resistance." (PMID 36789695, 2022). "Immunofluorescence (IF) staining combined with fluorescencein situ hybridization (FISH) of pancreatic cancer tissues shows that DSCR9 and BTG2 are both increased in pancreatic cancer tissues." (PMID 36789695, 2022). "BTG2 plasmid transduction attenuates the capacity of pancreatic cancer cells to proliferate and invade while enhancing cell apoptosis." (PMID 36789695, 2022). "BTG2 acts as a tumor suppressor by reducing the proliferation and invasion of pancreatic cancer cells and increasing gemcitabine-induced apoptosis." (PMID 36789695, 2022). "IHC staining revealed the protein content and distribution of BTG2 in tissue samples; as shown inFigure 3D, the number of BTG2-positive cells was much lower in pancreatic cancer tissues." (PMID 36789695, 2022). "The functions of the lncRNA DSCR9/miR-21-5p/BTG2 axis in new pancreatic cancer treatment strategies await further investigation." (PMID 36789695, 2022). "BTG2 also exerted tumor-suppressive effects by suppressing the proliferation and invasive ability of pancreatic cancer cells and increasing gemcitabine-stimulated apoptosis." (PMID 36789695, 2022). "Overexpression of miR-21-5p attenuates the effect of DSCR9 overexpression on BTG2 expression and invasiveness of pancreatic cancer cells." (PMID 36789695, 2022). "In conclusion, we demonstrated that the lncRNA DSCR9/miR-21-5p/BTG2 axis modulates pancreatic cancer proliferation, invasion, and resistance to gemcitabine." (PMID 36789695, 2022). "Under gemcitabine treatment, BTG2 overexpression also enhanced the promotive effects of gemcitabine on pancreatic cancer cell apoptosis." (PMID 36789695, 2022). "As we have mentioned, BTG2 exerts a tumor inhibitory effect on various cancers, such as pancreatic carcinoma." (PMID 36789695, 2022). "Pancreatic cancer-derived exosomal miR-27a promoted the development of pancreatic cancer via targeting BTG2." (PMID 33834074, 2021). "Pancreatic cancer cell-derived exosomes containing miR-27a promotes the vascularization of human microvascular endothelial cells through BTG2, thus promoting the occurrence and development of pancreatic cancer." (PMID 33828985, 2021). "Then, RT-qPCR and immunohistochemistry were used to detect BTG2 expression in pancreatic cancer tissues and adjacent normal tissues." (PMID 33425718, 2020). "CircRNA_000864 and BTG2 were poorly expressed, and miR-361-3p was highly expressed in the pancreatic cancer tissues." (PMID 33425718, 2020).